RNH1 (ribonuclease/angiogenin inhibitor 1)
Diseases named in the same sentence as RNH1 in open-access papers (continued):
Sharing a sentence is not in itself a finding about the gene and the disease.
malignant glioma (1 paper, 2024). A grade III or grade IV glioma arising from the central nervous system. "Published data on the three potential prognostic biomarkers identified, FABP7, MDH1 and RNH1, indicate that high levels of FABP7 are associated with a poor prognosis for patients with various types of tumors, including malignant gliomas." (PMID 38803161, 2024).
peritonitis (1 paper, 2022). Inflammation of the peritoneum (tissue that lines the abdominal wall and covers most of the organs in the abdomen). "Furthermore, Rnh1−/− mice also displayed increased neutrophil infiltration in MSU-induced peritonitis." (PMID 35256513, 2022). "Corroborating this, mouse models of monosodium urate (MSU)-induced peritonitis and lipopolysaccharide (LPS)-induced endotoxemia, which are dependent on caspase-1, respectively, show increased neutrophil infiltration and lethality in Rnh1−/− mice compared with wild-type mice." (PMID 35256513, 2022). "To investigate the in vivo role of RNH1 in inflammasome activation, we performed mouse models of caspase-1–dependent MSU-induced peritonitis and LPS-induced lethality." (PMID 35256513, 2022).
cancer (10 papers, 2014 to 2024). A tumor composed of atypical neoplastic, often pleomorphic cells that invade other tissues. "Taken together, we determined that RNH1 is aberrantly expressed in multiple cancers but is associated with prognosis in only a few types of cancer." (PMID 37537337, 2023). "First, we found that RNH1 is aberrantly expressed in multiple cancers but is associated with prognosis in only a few types of cancer." (PMID 37537337, 2023). "We found that RNH1 expression was significantly associated with OS or RFS in several cancer types." (PMID 37537337, 2023). "MA Sarangdhar and R Allam reviewed that the expression of RNH1 was reduced in cancer tissues, and overexpression of RNH1 in vitro weakened the ability of cell proliferation, migration and invasion." (PMID 38783241, 2024). "Biologically, RNH1 participates in processes such as angiogenin (RNase 5)-regulated neovascularization, monitoring of the cellular oxidative state, and cancer growth and metastasis." (PMID 38951571, 2024). "It has been reported that down-regulation of RNH1 promotes malignant behavior of cancer cells, but the role of RNH1 in LUAD is still unclear." (PMID 38783241, 2024). "First, we explored the expression of RNH1 in human cancers based on the TCGA, GTEx, and CPTAC databases." (PMID 37537337, 2023). "It is worth mentioning that our analysis revealed higher methylation levels of RNH1 in multiple cancer tissues than in normal tissues." (PMID 37537337, 2023). "In the present study, RNH1 was found to be abnormally expressed in various cancers based on pancancer analysis." (PMID 37537337, 2023). "The aberrant expression pattern of RNH1 in human cancers prompted us to explore its prognostic value." (PMID 37537337, 2023). "Although DNA methylation is an important factor affecting mRNA transcription, we found that the methylation level of RNH1 is very low in various cancer tissues." (PMID 37537337, 2023). "Consistently, RNH1 protein levels were low in tissues of multiple cancer types compared with healthy tissue." (PMID 37537337, 2023). "In this study, pancancer analysis indicated that RNH1 was aberrantly expressed in a variety of cancers." (PMID 37537337, 2023). "Next, we used the cBioPortal tool to analyse the genetic alteration status of RNH1 in different cancer types from the TCGA cohorts." (PMID 37537337, 2023). "Overall, both ANG and RNH1 strongly implicated in pathophysiology of number of cancers and understanding the precise mechanisms will be the key to target ANG-RNH1 system for anti-cancer therapies." (PMID 33525475, 2021). "Since RNH1 is up-regulated in a number of cancers, Ang-based hCFPs must comprise an Ang effector with reduced affinity for RNH1, such as by the introduction of large obstructing side chains at positions 85 and 86 (G85R and G86R)." (PMID 28536352, 2017). "There has been an increase in research studies to investigate the relationship between RNH1 and cancer." (PMID 24926661, 2014). "RNH1 regulates the localization and activity of angiogenin which is involved in cell growth and survival mechanisms as well as in cancer establishment, growth and metastasis." (PMID 25058392, 2014). "RNH1 protein levels were lower in cancer tissue than in adjacent tissue in all 20 LUAD patients." (PMID 38783241, 2024). "By regulating the LAMP2a/RNH1/miR‐99a/mTOR signaling axis to make anti‐cancer effects, aripiprazole administration may be an efficient strategy for CRC therapy." (PMID 39513392, 2024). "Ribonuclease/angiogenin inhibitor 1 (RNH1) exerts multiple roles in virous cancers." (PMID 38783241, 2024). "Besides, we determined mRNA expression of RNH1 in 40 pairs LUAD cancer tissues and adjacent normal tissues." (PMID 38783241, 2024). "Pancancer analyses were performed to explore whether there are commonalities in the function of RNH1 in human cancers and to explore its functional role." (PMID 37537337, 2023).
cancer (continued). "In terms of drug response, high expression of RNH1 could make cancer cells more sensitive to cetuximab." (PMID 37537337, 2023). "Similarly, we also used the cBioPortal analysis tool to determine the relationship between prognosis and RNH1 genetic alteration status across cancers." (PMID 37537337, 2023). "This suggests that multiple important roles of RNH1 in cancer deserve further exploration." (PMID 37537337, 2023). "Similarly, RNH1 expression was also significantly positively correlated with the levels of most immune cell infiltrates in several cancer types (USC, SARC, TGCT, LAML, and UVM)." (PMID 37537337, 2023). "Moreover, RNH1 has been shown to be downregulated in cancer tissues compared to adjacent normal tissues." (PMID 33525475, 2021). "This may be related to the low RNH1 expression in multiple cancer types." (PMID 37537337, 2023). "Knockdown of RNH1 promoted cell proliferation, tumorigenesis in vivo and EMT process, and drove cancer cell migration and invasion." (PMID 38783241, 2024). "We found that RNH1 was positively correlated with a majority of immunomodulators in BLCA based on TCGA data, but only a few in other cancer types." (PMID 37537337, 2023). "Nevertheless, the impact of RNH1 expression on OS and RFS varied depending on the cancer type." (PMID 37537337, 2023). "Additionally, we found that RNH1 exhibits a high rate of deep deletion among genetic alterations in most cancers, but we noted that the total frequency of RNH1 alteration is not high in various cancers." (PMID 37537337, 2023). "We found that the effect of RNH1 on the functional status of most cancers was not significant." (PMID 37537337, 2023).
tumor (9 papers, 2017 to 2025). "The hallmarks associated to RNH1 included angiogenesis (angiogenic deregulation), sustaining proliferative signalling (growth signals) and tumour promoting inflammation (oxidative stress)." (PMID 37784035, 2023). "Our results suggest that loss of RNH1 accelerated tumor growth and LUAD metastasis." (PMID 38783241, 2024). "RNH1 knockdown upregulated the expression of PCNA and MMP9, and RNH1 overexpression declined it, suggesting that RNH1 inhibited LUAD tumor formation in vivo." (PMID 38783241, 2024). "We further showed the differences in malignant behavior of tumor cells after co-overexpression of RNH1 and E2F1." (PMID 38783241, 2024). "Our study illustrated the importance of RNH1 in LUAD and the potential regulation between E2F1 and RNH1 in the process of tumor formation." (PMID 38783241, 2024). "Knockdown of RNH1 leads to upregulation of PCNA in tumor tissues, representing an increased proliferative capacity of cells." (PMID 38783241, 2024). "The tumor formation model was performed to illustrate the effects of RNH1 on tumor development in vivo." (PMID 38783241, 2024). "Meanwhile, RNH1 expression (both mRNA and protein levels) is frequently downregulated in CRC and correlates with poor prognosis in patients with CRC, suggesting a tumor‐suppressive role of RNH1 in CRC." (PMID 39513392, 2024). "It is generally known that RNH1 plays a role in tumorigenesis by affecting the functional status of tumours in terms of processes, such as cell differentiation, proliferation, invasion, migration, apoptosis, and cell cycle." (PMID 37537337, 2023). "Subsequently, we confirmed that RNH1 shapes an inflammatory tumour microenvironment (TME), promotes activation of the immune response cycle steps, and has the potential to predict the immune checkpoint blockade (ICB) treatment response." (PMID 37537337, 2023). "Further, the inhibitor of ANG, RNH1 has been shown to prevent tumor-induced angiogenesis and tumor growth." (PMID 33525475, 2021). "Since Ang-based hCFPs rely on cytoplasmic deployment of apoptosis-inducing Ang, target tumor cells can protect themselves by expressing inhibitor proteins such as RNH1 and rapidly neutralizing wild-type (WT) Ang." (PMID 28536352, 2017). "In addition, we analyzed 18 pairs of CRC tumor and adjacent normal tissues to determine the clinical significance of LAMP2a and RNH1 expression using western blot." (PMID 39513392, 2024). "High serum levels of MDH1 and RNH1 and low tumor levels of FABP7 may enable STS to maintain low ROS levels, counteracting the effects of chemoradiotherapy." (PMID 38803161, 2024). "The majority of tumor cases had a stronger expression of LAMP2a (66.7%) in tumors than in adjacent normal tissues, and only 27.5% and 16.7% of tumors had stronger protein and mRNA expression of RNH1 than adjacent normal tissues, respectively." (PMID 39513392, 2024). "RNH1 has been showed to inhibit tumor growth and tumor-induced angiogenesis." (PMID 38783241, 2024). "The results showed that mRNA expression of RNH1 was reduced in tumor tissue." (PMID 38783241, 2024). "Additionally, the expression level of RNH1 was higher in inflamed tumours than in immune excluded and immune desert tumours." (PMID 37537337, 2023). "This indicates that the expression of RNH1 is also related to the tumour immune response." (PMID 37537337, 2023). "To study the clinical relevance of LAMP2a and RNH1, we detected the expression of LAMP2a, RNH1, and mTOR in a tissue microarray containing 94 CRC tumor and 88 normal tissue samples, by means of multiplex immunohistochemistry staining." (PMID 39513392, 2024). "Most tumor tissues had higher LAMP2a expression than adjacent normal tissues, and 80% of tumor tissues displayed low RNH1 expression (negative and weak), whereas only 50% of normal tissues displayed low RNH1 expression." (PMID 39513392, 2024).
infection (4 papers, 2021 to 2024). The state of being infected such as from the introduction of a foreign agent such as serum, vaccine, antigenic substance or organism. "We have shown that RNH1-KO THP1 cells are susceptible to infection with SARS-CoV-2 pseudovirus." (PMID 35256513, 2022). "Lentiviral infection was constructed to silence or overexpress RNH1 in NCI-H1395 and NCI-H1437 cells." (PMID 38783241, 2024). "In brief, RNH1 is upregulated at the early stage of infection but downregulated after 2 weeks when comparing its expression in infected CD4+ T cells to non-infected ones." (PMID 34781942, 2021). "We provide functional evidence that lack of RNH1 in patient fibroblasts cause susceptibility toward extracellular RNases, which could explain the multiorgan manifestations and infection-induced deterioration." (PMID 36935417, 2023).
RNH1 also shares sentences with these, for which no sentence is quoted: colorectal cancer (2 papers); adrenocortical carcinoma (1); carcinoma in situ (1); colon cancer (1); dementia (1); developmental delay (1); intellectual disabilities (1); liver dysfunction (1); lung adenocarcinoma (1); macrocytic anemia (1); melanoma (1); myopathy (1); neurological diseases (1); Obesity (1); seminoma (1); upper respiratory tract infections (1); viral infection (1); Wilms tumor (1).